RN7SKP259 (RN7SK pseudogene 259)
Gene: Miscellaneous RNA gene on chromosome 11 (57,451,690 to 57,452,022, forward strand). Ensembl gene ENSG00000222998.
Homologues: Orthologues: chimpanzee 7SK (93% identical), guinea pig 7SK (59% identical), guinea pig 7SK (54% identical), guinea pig 7SK (52% identical). Paralogues in human: RN7SKP224 (67% identical), RN7SKP133 (67% identical), RN7SKP203 (67% identical), RN7SKP47 (66% identical), RN7SKP90 (65% identical), RN7SKP180 (65% identical), 7SK (65% identical), RN7SKP189 (65% identical), RN7SKP250 (65% identical), RN7SKP255 (65% identical), RN7SKP79 (65% identical), RN7SKP9 (64% identical), and 284 more.